ALB (albumin)
Diseases named in the same sentence as ALB in open-access papers (continued):
Sharing a sentence is not in itself a finding about the gene and the disease.
asthma (continued). "Consequently, we utilized data from the National Health and Nutrition Examination Survey (NHANES) 2011–2018 cycles to examine the connection between protein intake, serum albumin and BEOC in patients with asthma." (PMID 38835754, 2024). "In this study, baseline data, albumin concentration, anion gap (AG) and 30-d mortality data were retrieved from the Medical Information Mart for Intensive Care IV database (MIMIC-IV) for patients with asthma in the intensive care unit." (PMID 37803051, 2023). "Subjects with asthma were more likely to be sensitized to lipocalins (55.8% vs. 28.8%, p < 0.001) and albumin (17.1% vs. 5.4%, p = 0.003), but not to secretoglobin (91.7% vs. 94.6%, p = 0.342) than those without asthma." (PMID 37632243, 2023). "On the other hand, the frequency of overlap between the lipocalins and serum albumin was higher in individuals with asthma than those without asthma (21.3% vs. 5.2%)." (PMID 35984703, 2023). "The CRs for both SP-A and albumin in the present study are rather high, and the values are larger than the differences observed in cross-sectional studies between healthy subjects and patients with COPD and asthma." (PMID 31978133, 2020). "At baseline albumin levels in nasal secretion were not correlated with serum 25(OH)D3 or 1,25(OH)2D3 in the whole group and also not for asthma patients and healthy controls apart." (PMID 26545199, 2015). "However, univariable and multivariable regression analyses all suggested a negative connection of serum albumin with BEOC in asthma populations." (PMID 38835754, 2024). "The natural fragment of serum albumin, EPI-X4, has been identified as an endogenous peptide antagonist and inverse agonist of CXCR4, and novel CXCR4 antagonists developed on the basis of this feature can be used in the treatment of atopic dermatitis, asthma, and other CXCR4-related diseases." (PMID 39026682, 2024). "However, in univariate and multivariate regression models, there was a negative correlation of serum albumin with BEOC in asthma people." (PMID 38835754, 2024). "Similarly, individuals with asthma had higher rates of overlapping sensitization to prostatic kallikrein and serum albumin than those without asthma (13.8% vs. 3.4%)." (PMID 35984703, 2023). "Unfortunately, I could not find information on plasma albumin concentrations for asthma patients; nevertheless, we might suppose that in these patients the albumin concentration is in normal range." (PMID 32708755, 2020). "In asthma patients albumin was not correlated with any of the AMPs or IL-8." (PMID 26545199, 2015). "The binding capacity (specific IgE and IgG binding) of the newly formed MDI-albumin conjugates was assessed using sera from patients with MDI-isocyanate asthma and control subjects (patients with non-isocyanate asthma, no isocyanate exposure and healthy control subjects)." (PMID 22544379, 2013). "Although previous studies have suggested that albumin-corrected anion gap (ACAG) may be a predictor of mortality in critically ill patients in intensive care unit (ICU), its utility in the context of asthma has not been definitively established." (PMID 37803051, 2023).
septic shock (62 papers, 2012 to 2026). Shock caused by infection; frequently caused by gram negative bacteria, although some cases have been caused by other bacteria, viruses, fungi, and protozoa; characterized by fever, chills, tachycardia, tachypnea, and hypotension. "Based on previous studies, we have found that the improvement in the 28-day mortality rate of septic shock patients is associated with the administration of albumin within 24 h of ICU admission." (PMID 37089426, 2023). "A 20% albumin bolus markedly improves microcirculation in fluid-responsive patients with septic shock." (PMID 40475388, 2025). "Compared with patients in Tertile 3, those in Tertile 1 had significantly higher respiratory and heart rates, lower serum albumin and lymphocyte counts, and a higher incidence of invasive mechanical ventilation and septic shock (all p < 0.05)." (PMID 41170357, 2025). "A nomogram predicting 30-day mortality discharge for candidemia patients has been constructed, and the independent risk factors including Candida albicans, multiple organ dysfunction syndrome, septic shock, solid tumors, and decreased albumin." (PMID 39963405, 2025). "This study aimed to evaluate the prognostic ability of the initial sequential organ failure assessment (SOFA) score alone and combined with serum albumin levels for predicting 28-day mortality in patients with septic shock." (PMID 39459557, 2024). "In model 3 with the maximum covariates including age, sex, APACHE II score, PaO2/FIO2,vasopressor use, CRRT, CKD, AKI, septic shock, albumin, creatinine, leukocyte, and CRP, adjusted HR for in-hospital mortality was 2.640 (95%CI, 1.208–5.767,P = 0.015)." (PMID 36115956, 2022). "In previous studies, we found an indication of the benefits of albumin administration in septic shock patients, where the intensity of oxidative stress was higher." (PMID 34447316, 2021). "In 30 patients with septic shock albumin infusion improved endothelial skin function, possibly through its antioxidant activity." (PMID 33741039, 2021). "An ongoing trial (NCT03869385) was designed to assess the impact of 20% albumin with crystalloid with a target albumin level of > 30 g/L in patients with septic shock, with 28-day mortality as the primary endpoint." (PMID 33336259, 2020). "In this study, we reanalyzed the results from the ALBIOS study - which in 2014 compared the efficacy of the administration of albumin and crystalloids versus crystalloids alone in patients with septic shock - based on the new definition of septic shock." (PMID 30261898, 2018). "In the subgroup of patients with septic shock at enrollment (n = 1,121), however, those who received albumin had significantly lower 90-day mortality rates than those who received saline (44% versus 50%; relative risk, 0.87; 95% CI, 0.77 to 0.99; P = 0.03)." (PMID 25042164, 2014). "Following logistic regression, significant differences were observed between the two cohorts in terms of total protein (P=0.017, HR: 0.861; 95% CI: 0.761–0.974), albumin (P=0.005, HR: 0.740; 95% CI: 0.599–0.914), and septic shock (P=0.046, HR: 4.399; 95% CI:1.025–18.870)." (PMID 38912203, 2024). "Thus, this study aimed to evaluate the prognostic ability of the initial SOFA score alone and in combination with serum albumin levels for predicting 28-day mortality in patients with septic shock at ED admission." (PMID 39459557, 2024). "Moreover, in the 1121 patients with septic shock, 90-day mortality was lower in the albumin group (564 patients) than in the non-albumin group (43.6 vs. 49%, p = 0.03)." (PMID 33287911, 2020). "Thus it was recently reported that incidence of RRT in a cohort of patients with septic shock resuscitated with mainly Ringers acetate was lower than in historical controls resuscitated with a combination isotonic saline, albumin and dextran-70 (23% vs 48%)." (PMID 28683810, 2017).
septic shock (continued). "SIC on day 4 was an independent risk factor for 28-day mortality after adjusting for age, D-dimer, albumin, and lactate levels, SOFA score, APACHE II score, and septic shock, whereas SIC on day 2 was not independently associated with mortality." (PMID 38438863, 2024). "In this survey, pediatric physicians used albumin as a volume expander despite a lack of evidence showing superiority over crystalloids in both adults and children with septic shock." (PMID 31254125, 2019). "A post hoc subgroup analysis which looked at septic shock patients (>1,100 of the 1,800) showed that albumin-treated patients with septic shock did demonstrate decrease in mortality at 90 days, whereas the albumin-treated group in patients without septic shock had an increased mortality." (PMID 25625012, 2014). "Moreover, the albumin administration in the early phase could also reduce disease severity in ARDS patients and improve vascular endothelial function in septic shock patients." (PMID 37089426, 2023).
cholestasis (61 papers, 1991 to 2026). Impairment of the bile flow caused by obstruction within the liver, or outside the liver in the bile duct system. "It is well-known that levels of total bilirubin, a serum cholestasis marker, and albumin are linked with central venous pressure in patients with HF." (PMID 34830658, 2021). "Generally, elevated bilirubin, a serum cholestasis marker, is related to acute liver congestion, and decreased albumin is associated with chronic congestive hepatopathy and poor prognosis in HF patients." (PMID 34830658, 2021). "In group 1, associations were observed between cholestasis severity and BMI (R = -0.3; P = 0.01) and ALB levels (R = -0.3; P = 0.01) and between severity of ductular proliferation and BMI (R = -0.3; P = 0.005) and ALB levels (R = -0.2; P = 0.04)." (PMID 34161522, 2021). "The ALBI score is based only on albumin and bilirubin, focusing on liver synthetic function and cholestasis." (PMID 40936688, 2025). "Instead, Lp-X accumulates in the plasma during cholestasis when bile lipids reflux into circulation and subsequently bind to albumin." (PMID 40995304, 2025). "In contrast, bilirubin and ASAT levels were significantly elevated, and albumin decreased in the cholestasis group." (PMID 37072399, 2023). "Similar albumin levels can be explained by early exclusion of animals with clinical signs of cholestasis, thus preventing liver damage." (PMID 37386088, 2023). "In contrast, albumin, identified as the third mostsignificantfeature, has not been directly linked to cholestasis before." (PMID 40421892, 2025). "However, in response to cholestasis, wild-type hepatocytes persistently increased albumin production, whereas Nrf2-null hepatocytes did oppositely." (PMID 35696363, 2022). "After multiple regression, it was observed that both ALB (R = -0.2; P = 0.02) and BMI (R = -0.2; P = 0.02) were independently correlated with cholestasis severity and that BMI (R = -0.2; P = 0.008) was independently correlated with the severity of ductular proliferation." (PMID 34161522, 2021). "Moreover, bilirubin’s affinity for albumin and other lipoproteins is disrupted by numerous agents in bile that are upregulated specifically in cholestasis." (PMID 30657454, 2019). "In contrast, several other metabolites are elevated in addition to bilirubin in cholestasis, many of which may alter the equilibrium between bilirubin and albumin." (PMID 30657454, 2019). "Cholestasis and decreased protein intake and synthesis (indicative by the clinical pathology panel) may also attribute in decreased albumin/globulin." (PMID 23472182, 2013). "There are few reports on the decrease of PLT and ALB (before treatments) caused by CCA; however, the obstruction and cholestasis caused by CCA could lead to hepatocellular damage (Shin, Moon & Kim, 2023), which also has the possibility of influencing the levels of PLT and ALB." (PMID 40708828, 2025). "We conclude that prolonged jaundice adversely affects the metaboliccapacity of the rats, with albumin concentration being markedly decreased, and that biliary decompressioncould not reverse completely all the alterations seen with cholestasis, especially following twoweeks of bile duct obstruction." (PMID 1777409, 1991). "Second, the results of liver function tests showed that biomarkers of liver damage (ALT, AST) and cholestasis (TBIL, GGT) exceeded the upper limit of normal range in most of the HSOS patients, while ALB exhibited different degrees of reduction." (PMID 34741082, 2021). "Serum markers reflective of liver injury (AST and ALT), cholestasis (ALKP), or liver function (albumin, total protein and total bilirubin) were assessed in animals at euthanasia." (PMID 27851786, 2016). "The negative findings for TBIL/ALB ratio further exclude widespread hepatocyte damage or cholestasis as primary driving factors, confirming the selective, specific regulation of hepatic protein synthesis function by inflammatory and metabolic signals." (PMID 41458520, 2025).
cholestasis (continued). "Plasma markers of synthetic liver function (total protein, albumin) and cholestasis (bilirubin, alkaline phosphatase) were normal." (PMID 36805337, 2023). "More indicators of liver function and cholestasis, such as AST, ALT, ALB, GGT, and ALP, may be screened in future studies to identify a comprehensive indicator that can reflect the efficiency of biliary drainage." (PMID 36439415, 2022). "To gain insight into the mechanisms involved in albumin dialysis, we analyzed the peptides and proteins absorbed into the MARS strong anion exchange (SAX) cartridges as a result of the treatment of patients with cholestasis and resistant pruritus." (PMID 21779339, 2011). "As a result, predictors tied to hepatic reserve or cholestasis—albumin and γ‐GT—may not carry identical weights, and baseline distributions could shift, affecting calibration and potentially effect sizes." (PMID 41331584, 2025). "However, neither GGT in serum indicating cholestasis nor inflammatory markers such as total leukocytes or albumin were significantly influenced after 15 weeks of GLY exposure." (PMID 37174536, 2023). "Furthermore, bilirubin and albumin levels may vary depending on nutrition status, drug use or cholestasis and are biased by different half-life times and thus are not the most reliable indicators of liver function." (PMID 23029162, 2012). "In this study, we also assessed the changes in GGT, ALP, serum bilirubin and serum albumin levels and none of the patients had significant elevations in ALP or serum bilirubin, which suggests that there was minimal cholestasis." (PMID 27391896, 2016). "This reflects distinct biological mechanisms: ALB and PA are negative acute-phase proteins specifically regulated by inflammatory-metabolic stress, while total bilirubin is influenced by WBC-related hemolysis, oxidative stress, and cholestasis." (PMID 41458520, 2025).
renal fibrosis (60 papers, 2012 to 2026). A final common manifestation of a wide variety of chronic kidney diseases characterized by glomerulosclerosis and tubulointerstitial fibrosis. "Long-term galantamine treatment improved survival; lowered blood pressure; reduced renal injury markers, including urinary albumin, kidney injury molecule-1, and neutrophil gelatinase-associated lipocalin; and decreased renal fibrosis in female mice with SLE." (PMID 42003680, 2026). "Hypoxia reduced the number of glomeruli in male offspring, and this was associated with glomerular hypertrophy, renal fibrosis and increased albumin excretion by 12 months of age." (PMID 28811528, 2017). "Glomerular number was reduced by 25% in hypoxia-exposed male, but not female, offspring and this was associated with increased urinary albumin excretion, glomerular hypertrophy and renal fibrosis." (PMID 28811528, 2017). "Actually, B6 mouse was found to be resistant to renal fibrosis in bovine serum albumin (BSA)-injected proteinuria model, but be susceptible to renal fibrosis in UUO model." (PMID 27230548, 2016). "Multivariate logistic regression analysis, adjusted for age, gender, albumin, and hemoglobin, revealed that higher serum copper levels (Quartile 4: > 96.16 μg/dl) were independently associated with higher renal fibrosis (OR = 2.75, 95% CI = 1.06–7.16, p < 0.001)." (PMID 40927337, 2025). "Restricting protein intake can protect the kidneys and slow the advancement of CKD by decreasing albumin levels and reducing renal fibrosis." (PMID 40142234, 2025). "In parallel, the urinary albumin–creatinine ratio is reduced by attenuating proximal tubular injury and renal fibrosis." (PMID 39861148, 2025). "The results of the study demonstrated that α-MT significantly reduced the urinary excretion of albumin and creatinine, improved kidney function, and decreased renal fibrosis in db/db mice." (PMID 39902076, 2024). "YSPDP markedly hindered CKD progression, characterized by the restoration of body weight and serum albumin levels, improved renal function, diminished tissue injury, and hampered renal fibrosis in 5/6 SNx rats." (PMID 39669205, 2024). "In this study, our primary objective was to examine the impact of Tempol on renal fibrosis, oxidative stress, and inflammation in 5/6 nephrectomy rats utilizing oxidized albumin as a biomarker." (PMID 38395806, 2024). "A study reported that BMMSCs can decrease levels of tubular CCL-2, CCL-5, TNF-α, α-SMA, fibronectin (FN), and collagen IV and finally reduce tubular EMT and renal fibrosis in albumin-overloaded mice." (PMID 36268508, 2022). "LIPUS treatment effectively alleviated the decreases in the body weight and albumin/globulin ratio and the increases in the serum renal functional markers, fibroblast growth factor-23, renal pathological changes, and renal fibrosis in the CKD mice." (PMID 36362179, 2022). "A long-acting carbohydrate-deficient BMP7 prepared by combining albumin fusion technology and site-specific mutagenesis showed a sustained renoprotective activity in the mice model of UUO-induced renal fibrosis and cisplatin-induced AKI." (PMID 35890230, 2022). "We found in established renal fibrosis, PA-S14 also decreased urinary albumin secretion, inhibited tubular injury and retarded renal fibrosis." (PMID 36276641, 2022). "The results showed a significant improvement in glucose intolerance, blood urea nitrogen, urine albumin, serum creatinine, and renal fibrosis in db/db mice with QDD treatment." (PMID 36091599, 2022). "Ang1-7 supplementation to these mice not only reduced renal mesangial expansion and urinary albumin secretion, but also ameliorated renal fibrosis and PRAT oxidative stress and inflammation mainly through the attenuation of NOX-mediated ROS production." (PMID 34408726, 2021).